SHANK3 (SH3 and multiple ankyrin repeat domains 3)
Diseases named in the same sentence as SHANK3 in open-access papers (continued):
Sharing a sentence is not in itself a finding about the gene and the disease.
Anxiety (61 papers, 2010 to 2026). Intense feelings of nervousness, tension, or panic often arise in response to interpersonal stresses. "In contrast, loss of Shank3 led to increased anxiety-like behavior, disruption of motor coordination, and reduced social preference that became more pronounced in adult mice relative to juvenile mice." (PMID 39633421, 2024). "Mutations in mouse Shank3 lead to a number of behavioural changes, including an increase in repetitive routines, altered social behaviour and anxiety-like phenotypes." (PMID 36833409, 2023). "Mice with SHANK3 deficiency display various behavioral deficits such as enhanced self-grooming, novelty-induced anxiety, and learning and memory deficiencies." (PMID 38002499, 2023). "At 9 months of age, Shank3 deficiency combined with 3xTg-AD transgenes displayed additive effects on the anxiety-like behavior, while at 12 months the expression of 3xTg-AD transgenes on one allele was sufficient to induce the change." (PMID 37253603, 2023). "To corroborate that anxiety was unchanged after mTBI, we also performed the open field and saw that Shank3-deficient mice preferred to spend more time on the arena border, and this behavior was not exacerbated with the mTBI intervention." (PMID 35682760, 2022). "Previously, we have demonstrated that mice deficient in Shank3 display a wide range of behavioral abnormalities such as repetitive grooming, social deficits, anxiety, and motor abnormalities." (PMID 32327468, 2020). "We observed that the supplemented maternal zinc diet prevented ASD-associated deficits in social interaction and normalised anxiety behaviours in Shank3−/− offspring mice." (PMID 32758248, 2020). "The dark-light emergence test was used to examine anxiety-associated behaviours in wildtype and Shank3−/− mice." (PMID 32758248, 2020). "Our data suggest that the Shank3 Q321R mutation in mice has significant influences on Shank3 protein stability, hippocampal neuronal excitability, anxiety-like and repetitive behaviors, EEG, and seizure susceptibility." (PMID 31275112, 2019). "Analogously, we observed impaired learning and memory, increased anxiety behavior, an increased baseline mechanical pain threshold and reduced temperature sensation in Shank3-deficient rats." (PMID 30971895, 2019). "Impaired learning and memory and increased anxiety behavior have often been reported in a majority of Shank3-deficient mouse models." (PMID 30971895, 2019). "Deletion of Shank3 caused deficits in motor function, heightened anxiety, and repetitive behaviors." (PMID 39633421, 2024). "Elevated anxiety levels were also replicated in conditional KO-strategies, inducing SHANK3 deficiency in somatosensory neurons or cells derived from the caudal embryo (ex13-16|PDZ-AdvillinCre or -Cdx2Cre), but also in GABAergic (ex14-16|PDZ-ViaatCre) or DRD1-positive neurons (ex4-22|ALL-Drd1Cre)." (PMID 34784886, 2021). "Deletion of SHANK3 could underlie high levels of anxiety and problems with adaptive behavior in this individual." (PMID 34228749, 2021). "In addition, impaired learning and memory, increased anxiety-like behavior, increased mechanical pain threshold and decreased thermal sensation were observed in Shank3-deficient rats." (PMID 30971895, 2019). "RESULTS: Treatment with 7-NI improved ASD-like behavioral deficits in Cntnap2 and Shank3 mutant mice, including increased sociability and reduced anxiety-like behavior." (PMID 42010670, 2026). "US research spans broader environmental factors (e.g., prenatal pollution, chemical exposures), genetic explorations (e.g., SHANK3 mutations), neuroimaging techniques (fMRI, DTI), and comorbidity with conditions like ADHD and anxiety." (PMID 40343096, 2025). "Mutations of ADNP and SHANK3 impair the binding of ADNP and Shank3 to actin leading to autistic behaviors, anxiety, and depression due to synaptic dysfunctions." (PMID 39223276, 2025).
Anxiety (continued). "The increased avoidance of the open/exposed areas in both assays is indicative of heightened anxiety-like behavior with reduced Shank3 expression that escalates during the juvenile to adult transition." (PMID 39633421, 2024). "Determining the Shank3-brain region interactions that drive Shank3-dependent changes in anxiety, motor function, social interactions, communication, and some forms of learning is crucial for understanding and treating PMS, and possibly ASD." (PMID 39633421, 2024). "At 3 months of age, Shank3Δ11/Δ11 mice, from Cohort 1 and 2, displayed typical body weight, anxiety-like behavior levels and working memory, compared to Shank3+/+ littermates." (PMID 37008785, 2023). "Behavioral tests were performed to determine the impact of Shank3 deficit on recognition memory, anxiety, and locomotion in mice over time." (PMID 37253603, 2023). "Our previous studies revealed that dietary zinc supplementation can normalise impaired social behaviours, excessive grooming, and heightened anxiety in a Shank3 mouse model of ASD, as well as the amelioration of synapse dysfunction." (PMID 35303947, 2022). "Chronic treatment of SHANK3-mutant mice additionally improved body condition, brain abnormalities in the somatosensory cortex, anxiety-like behaviors, social deficits, avoidance behavior, and hypoactivity." (PMID 34784886, 2021). "Our results indicate that Avidekel oil can alleviate excessive repetitive grooming and anxiety behaviors in InsG3680 Shank3 mutant mice." (PMID 34645786, 2021). "This suggests that maternal zinc supplementation caused changes in the developing brain of Shank3−/− offspring that led to a sustained prevention of ASD-associated repetitive behaviours, anxiety, and deficits in social interaction." (PMID 32758248, 2020). "B) Shank3 HT KI mutant mice still manifest core phenotypes, whereas other tested behavior is more like wild-type mice, like normal anxiety, sensorimotor gating, and spatial learning." (PMID 30911366, 2019). "As presented here, a number of the most frequent ASD-related phenotypes, like social behavior and anxiety, are assessed in Shank3 models." (PMID 30911366, 2019). "Although the restoration of Shank3 expression promoted dendritic spine growth and recovered normal grooming behavior and voluntary social interaction, reduced locomotion, increased anxiety, and social interaction deficits persisted in adult mice with inducible Shank3 knockout." (PMID 37947623, 2023). "Behavioral phenotypes, like increased repetitive routines, abnormal social behavior, elevated anxiety levels, impaired neuronal physiology, and altered PSD levels of HOMER, DLGAPs, NMDARs, AMPARs and other proteins, typify SHANK3-deficient murine animal models." (PMID 34784886, 2021). "Finally, differential deletion of SHANK3 either affecting DRD1- or DRD2-positive neurons (ex4-22|ALL-Drd1Cre or -Drd2Cre) resulted in a minor anxiety-like phenotype and increased repetitive behavior, respectively." (PMID 34784886, 2021). "When induced at P10, SHANK3 deficiency did not result in avoidance behavior, anxiety, or an abnormal number of PVALB-neurons in the amygdala." (PMID 34784886, 2021). "Additionally, InsG3680 Shank3 mutant mice treated with Avidekel oil spent significantly more time exploring the open arms in the elevated plus maze, indicating lower levels of anxiety." (PMID 34645786, 2021).
Anxiety (continued). "Therefore, GABA neuronal Shank3 deletion seems to be more important for social and locomotor behaviors than repetitive and anxiety-like behaviors." (PMID 30356810, 2018). "We found that GABA neuron-specific Shank3 deletion induces a strong reduction in excitatory synaptic input onto dorsolateral striatal neurons and abnormal social and locomotor behaviors, while having moderate effects on repetitive and anxiety-like behaviors." (PMID 30356810, 2018). "Therefore, GABAergic Shank3 deletion seems to strongly contribute to the anxiety-like behavior of global Shank3Δ14–16 mice in the light-dark test." (PMID 30356810, 2018). "However, there are few reports on the relationship between SHANK3 and anxiety." (PMID 38676295, 2024). "On the other hand, Shank3-deficient animals showed anxiety independent of the injury." (PMID 35682760, 2022). "Increased anxiety has been observed in various, but not all murine models of SHANK3 deficiency." (PMID 34784886, 2021). "The adverse effect of FMT ASD was further demonstrated in Shank3−/− mice by the shortest time spent in the open arms of the EPM, corresponding to the most prominent anxiety-like behavior among the murine groups." (PMID 40649705, 2025). "We recently reported that Shank3 mutant dogs, generated by CRISPR/Cas9 editing, exhibited ASD-like behaviors, such as social withdrawal, elevated anxiety, and hypersensitive to deviant tones, indicating that these dogs were effective ASD animal models." (PMID 38297387, 2024). "A notable observation is that Shank3 defects synergized with APP/tau transgenes to impair object recognition and precipitate anxiety-like behavior." (PMID 37253603, 2023). "Both “Anxiety” and “Self-grooming” were increased in all tested HM KO mouse models indicating a strong recapitulation of human ASD phenotypes in Shank3 KOs." (PMID 30911366, 2019). "Previous studies experimenting with the Shank3 model we use in our study (SHANK3b), where the SH3 domain is abolished (exon 13–16), have reported varied anxiety-like behaviors." (PMID 31624228, 2019). "In the elevated zero-maze, a reduction of anxiety was observed in both the C57 and FVB strain Shank3 mutant animals, and the number of entries into an open arc was increased in 129SVE and C57 knockout mice." (PMID 24652766, 2014). "Another team reported no anxiety-like behavior in 5 to 9-week-old Shank3−/− mice, replicating the result in a subsequent paper." (PMID 40753218, 2025). "Additional analysis showed that 2‐DG treatment did not affect the anxiety‐like and repetitive behaviors of Shank3−/− mice (Fig EV3F–H)." (PMID 37078424, 2023). "The time spent grooming was not significantly different between Shank3+/+, Shank3Venus/+, and Shank3Venus/Venus mice, suggesting the absence of stereotyped behavior and no atypical anxiety level in Venus-tagged Shank3a mice." (PMID 36570823, 2022). "We found that CBD oil alone does not change significantly the anxiety, social, locomotor and repetitive grooming behaviors performed by InsG3680 Shank3 mutant mice compared to olive oil treatment." (PMID 34645786, 2021). "Reexpression of SHANK3 at this later timepoint did not influence certain abnormal somatosensory properties, social recognition, avoidance behavior, anxiety-like behaviors, and long-term recognition memory deficits." (PMID 34784886, 2021).
Anxiety (continued). "Strikingly, adult Shank3 restoration rescued synaptic protein composition, repetitive behaviors, and social interaction deficits, but not anxiety or motor performance, which were rescued only when Shank3 was reactivated at juvenile ages." (PMID 33616084, 2021). "Rat models of Shank3 display some deficits in social behavior (long-term memory) but do not share several of the phenotypes displayed by mouse Shank3 models, like no impairments in ultrasonic vocalization or changes in anxiety levels are observed in rats." (PMID 30911366, 2019). "In line with this, re-expression of Shank3 in adult mice that developed in absence of Shank3 was able to rescue social interaction deficits and repetitive grooming behavior, but not anxiety and motor coordination deficits." (PMID 29875651, 2018). "In addition, the abnormal social and locomotor behaviors observed in global Shank3-mutant mice are strongly mimicked by GABA neuron-specific Shank3-mutant mice, whereas the repetitive and anxiety-like behaviors are only partially mimicked." (PMID 30356810, 2018). "Evaluation of wildtype, heterozygous, and knockout mice on behavioral assays across a range of domains, including anxiety-like, motor, exploratory, memory, and social behavior, revealed that behavioral changes in the absence of Shank3 fell into three categories." (PMID 39633421, 2024). "Anxiety is reported in Shank3 animal models but is not a common clinical feature in human studies." (PMID 37441676, 2023). "Social and cognitive deficits are largely, but not completely rescued upon adult reinstatement of Grin1 and fully rescued upon Shank3 reinstatement, but motor and anxiety deficits are only partially rescued upon Grin1 reinstatement and not rescued upon Shank3 reinstatement." (PMID 36304100, 2022). "However, complete rescue of ASD behaviours was not achieved, with anxiety and motor coordination deficits remaining after Shank3 restoration." (PMID 35002604, 2021). "The absence of increased anxiety also hints at the presence of further modifying factors in S100B exposed mice or Shank2 and Shank3 KO mice that modulate the phenotype, such as extracerebral factors like gastrointestinal abnormalities that, for example, have been reported in Shank3 KO mouse models." (PMID 34741005, 2021). "In contrast, GABAergic Shank3 deletion seems to have minimal impacts on the anxiety-like behavior in the elevated plus-maze test, suggesting that non-GABAergic Shank3 deletions are more important for the anxiolytic-like behaivor of global Shank3Δ14–16 mice in the elevated plus-maze." (PMID 30356810, 2018). "Several studies of monogenetic (Shank3, Cntnap2) or environmental (maternal HFD) ASD report no benefit of LR in reducing hyperactivity or anxiety in male or female offspring." (PMID 39520540, 2025). "In a SHANK3 model of ASD, morphological, functional, and behavioral anomalies such as self-injurious grooming and social interaction deficits (but not anxiety or motor deficits) are reversible in adult mice." (PMID 38129387, 2023). "Thus, the finding that adult restoration of SHANK3-expression in a cKI ex13-16|PDZ murine model reversed repetitive self-injurious grooming and social-interaction deficits is of great importance, although anxiety or motor coordination deficits were not alleviated." (PMID 34784886, 2021).
developmental delay (30 papers, 2010 to 2025). "Similar results support the effect that 22q13 gene deletions and SHANK3 point mutations have on various clinical manifestations, such as developmental delay and language impairment." (PMID 35864987, 2022). "Further analysis of this and additional models may identify targets for novel therapeutics for individuals with developmental delays arising from 22q13 deletion syndrome or SHANK3 mutations." (PMID 21167025, 2010). "As Shank3 is known to be highly expressed in placenta, this suggests that Shank3 deficiency could lead to placental insufficiency responsible for in utero developmental delays and increased perinatal mortality." (PMID 30302388, 2018). "Indeed, novel SHANK3 variants are more and more often detected in individuals with unexplained developmental delay or ASD, as a result of the increasing use of next-generation sequencing in routine genetic diagnosis (syndrome-targeted panel, whole exome or whole genome sequencing)." (PMID 26489495, 2015). "As a recurrent microdeletion syndrome, 22q13.3 deletion syndrome has been well characterized and SHANK3 has been designated as the key gene to elucidate the neurological symptoms like developmental delay and autistic-like behavior." (PMID 34128868, 2021). "It is estimated that the rates of mutation of SHANK3 in ASD and developmental delay are in the same range as deletions, so PMS due to mutation in SHANK3 will be increasingly identified." (PMID 25784960, 2014). "Given the multitude of functions that depend on proper SHANK3 levels, it is not surprising that this variant in the SHANK3 gene has been associated with global developmental delays and significant issues with speech, as well as poor muscle tone." (PMID 35216282, 2022). "SHANK3 is within the region of the chromosome 22q13.3 deletion syndrome, which is characterized by neonatal hypotonia, global developmental delay, severe cognitive deficits, normal to accelerated growth, absent to severely delayed speech, autistic behaviour, and minor dysmorphic features." (PMID 23300510, 2012). "Finally, several recent studies demonstrated that even de novo point mutations in SHANK3 can produce the entirety of neurodevelopmental symptoms of 22q13DS, including global developmental delay, absent or severely delayed expressive speech, and ASDs." (PMID 21167025, 2010). "In the Canadian family, the elder sister carrying the SHANK3 duplication was diagnosed with attention-deficit/hyperactivity disorder (ADHD) and developmental delay." (PMID 25188300, 2014). "We note that SHANK3 haploinsufficiency remains underdiagnosed in ASD and developmental delay, although with the increasingly widespread use of chromosomal microarray analysis and targeted sequencing of SHANK3, the number of cases is bound to rise." (PMID 23758743, 2013). "Therapeutic approaches that reverse deficits in SHANK3-haploinsufficiency may therefore be broadly beneficial in ASD and in developmental delay." (PMID 23621888, 2013). "Furthermore, early evidence has been published for the use of zinc in Phelan-McDermid syndrome, which is a single SHANK3 deletion syndrome or haploinsufficiency, characterized by global developmental delays, decreased muscle tone, difficulties with or absence of speech, and ASD." (PMID 35216282, 2022). "We used an hiPSC line generated from a 4-year-old male, diagnosed with ASD and developmental delay but not PMS, with a SHANK3 gene deletion starting at the third intron and continuing just beyond the end of the gene on chromosome 22q." (PMID 30064494, 2018).